IL6 (interleukin 6)
Diseases named in the same sentence as IL6 in open-access papers (continued):
Sharing a sentence is not in itself a finding about the gene and the disease.
cancer (continued). "Lastly, given the shared role of IL-6 and miR-31 in cancer stem cell function, and the OSCC-specific increase in salivary IL-6 mRNA, adding IL-6 mRNA to the miRNA biomarker panel may improve both the sensitivity and specificity of OSCC detection." (PMID 35215172, 2022). "Cancer-related muscle wasting has been attributed to circulating, i.e., systemic inflammatory, prooxidative, or other catabolic factors of tumor or multiple host origins, such as TNF, IL6, PIF, ZAG, or the more recently identified IL8 or MyD88." (PMID 35626644, 2022). "Cancer cell migration, invasion, and proliferation have been found to be supported by a number of proinflammatory mediators, for example, interferon-γ (IFN-γ), interleukin-6 (IL-6), and tumor necrosis factor α (TNF-α)." (PMID 36531650, 2022). "Investigation of anti-cancer mechanisms of tubulosine, originally isolated from bark of Pogonopus tubulosus in 1964, identified tubulosine as a potent inhibitor of JAK2/STAT3 signaling through disruption of IL-6/IL-6Rα/gp130 complex formation." (PMID 35371975, 2022). "Research has indicated that up-regulation of the pro-inflammatory cytokines IL-6, TNF-a, and IFN-γ secreted by cancer tissues could prevent the differentiation of pre-adipocytes and cause-altered phenotypes." (PMID 35756650, 2022). "Unique pathophysiological changes are still under examination, but several studies have shown that prognostic biomarkers, such as CRP, D-dimer, prothrombin time, and serum IL-6 levels, were significantly higher in cancer patients than in non-cancer patients." (PMID 35466178, 2022). "Despite the augmented levels of MIP-1α and IL-6 pro-inflammatory mediators in the cancer compartment, these did not affect overall osteoclast resorption activity nor resorption mode in the bone compartment." (PMID 35243294, 2022). "STAT3 is not only a downstream target of IL-6, but, along with miR-181b-1, miR-21, PTEN and CYLD, lysine 63 deubiquitinase is part of the positive feedback loop regulating the epigenetic switch linking inflammation to cancer." (PMID 36010971, 2022). "A wide range of therapeutic approaches including anti-IL-6 or anti-IL-6 receptor antibodies, soluble gp130Fc and selective small molecule JAKs inhibitors have been created to block the IL-6/STAT3 pathway for treating human cancers." (PMID 35954156, 2022). "Increased TNF-α secretion caused by Fusobacterium nucleatum infection modulates the expression levels of the cancer-carcinogenic target MiR-21, which in turn modulates the secretion of additional inflammatory cytokines, including TNF-α, IL-6, IL-17A, and IL-21." (PMID 36140470, 2022). "As a negative prognostic factor in cancer, IL-6 has been shown to be an important regulator of MDSC accumulation and activation." (PMID 35548349, 2022). "Our preclinical studies in a GC cancer model driven by the absence of NF-κB1, have shown that genetic deletion of IL-6 is dispensable for the development of GC, with a minor role for IL-6 at the early stages of gastric dysplasia." (PMID 35844493, 2022). "Both IL6 and IL8 are pro-inflammatory cytokines, and although inflammation represents a necessary component in tissue regeneration and vascularization, de-regulation and high levels of both can contribute to chronic inflammation and cancer development." (PMID 35782511, 2022). "This pathway is activated in ALDHhigh and CD126+ endometrial CSCs by IL-6, which also converts the nonstem cancer cells into cancer stem cells by activating the downstream Oct4 gene, in the case of breast CSCs." (PMID 35800881, 2022). "Previous studies showed that IL-6, HSP70/90 and miRNAs in cancer exosomes could participate in triggering muscle degradation, emphasizing the important roles of cancer exosomes in the development of cancer cachexia." (PMID 35379793, 2022).
cancer (continued). "To this end, we compared the relationships between OM grade, oral mucosal dryness, and inflammatory mediators (Interleukin (IL)-1β, IL-6, IL-10, IL-12p70, tumor necrosis factor (TNF), prostaglandin E2, and vascular endothelial growth factor) in patients with cancer and in healthy volunteers (HV)." (PMID 35476641, 2022). "In addition, we recently found that the CAF-derived IL-6/8-JAK2 signaling cascade can promote BRD4 phosphorylation, a critical epigenetic regulator in the regulation of cancer cell stemness." (PMID 36627901, 2022). "Following activation of the STAT3 pathway due to TAM-derived IL-6, tumor suppressor miR-204-5p expression significantly decreased, increasing in the anti-apoptotic protein RAB22A and B-cell lymphoma 2 (Bcl2) expressions in cancer cells." (PMID 35784290, 2022). "IL-1, IL-6, and TNF-α play an essential role at the systemic level as inducers of cancer cachexia." (PMID 36072935, 2022). "Several studies have suggested that IFs are related to the development and prognosis of cancer, among which TNF-α and IL-6 are the most typical cytokines related to inflammation, which can play an important role in host defense by regulating immune and inflammatory responses." (PMID 36284990, 2022). "The IL-6/JAK1 pathway induces PD-L1 Y112 phosphorylation, leading to cancer immune evasion." (PMID 36479088, 2022). "Inflammation, cancer, and immunological illnesses may all be traced back to the main active molecules inside organisms, such as TNF-α and IL-6, which perform integral roles in the pathogenesis of these conditions." (PMID 36032961, 2022). "Our results confirmed that human TNF-α and IL-6 were capable of inducing mouse myotube atrophy, indicating that the in vitro murine C2C12 myotube model can be applied for assessing cancer cachexia induced by human cancer cells." (PMID 36471329, 2022). "We identified IL6 as an important lynchpin between ICD and cancer." (PMID 36497433, 2022). "Whereas these cytokines may lead to co-occurring immune stimulation and immunosuppression in cancer patients, concentrations of cytokines MIF, TNFα, interleukin 6, interleukin 8, interleukin 10, interleukin 18, and TGFβ are increased." (PMID 36579330, 2022). "IL-6, TNF- α are inflammatory markers and their elevated level promotes cancer progression." (PMID 36330087, 2022). "On the other hand, the IL-6/STAT3 pathway increases miR-92a and miR-18a expression by directly targeting its promoter, which resulted in the activation of the Wnt/β-catenin signaling pathway and the promotion of the stem-like phenotype of cancer cells." (PMID 36499093, 2022). "In different types of tumors, cancer cells produce factors involved in the myelopoiesis (VEGF, GM-CSF, IL-1β, IL-6, HIF-1α, TGF-β, COX-2), as well as in the recruitment (CCL2, CCL3) and activation (TNF-α, IL-10, IL-1β, IL-6, INF-γ, COX-2, HIF-1α) of MDSCs." (PMID 35160177, 2022). "Plasma levels of IL-6 and IL-8 in cancer patients with metastases were higher than those without metastases (P < 0.05)." (PMID 36157224, 2022). "Ligation of IL-6 with IL-6R activates Janus kinase (JAK) tyrosine kinases leading to phosphorylation of signal transducer and activator of transcription 3 (STAT3), which is a well-studied cancer signaling pathway." (PMID 35924148, 2022). "Importantly, CAFs can secrete proinflammatory cytokines, such as interleukin (IL)-6, which promotes the EMT of cancer cells, forming a positive feedback loop." (PMID 36010899, 2022). "In as much as IL-6 and STAT3 activation can enhance the proliferation of cancer cells in various solid tumors as well as hematopoietic malignancies, considerable effort is now focused on the development of STAT3 inhibitors as anti-cancer agents." (PMID 35406728, 2022). "IL6 is a pleiotropic cytokine that can induce the epithelial-mesenchymal transition (EMT) of cancer cells, thereby enhancing the invasiveness and distant metastasis ability of cancer cells." (PMID 35590327, 2022).
cancer (continued). "Although these researchers did not clarify the contribution of cancer-derived EVs to iCAF differentiation, they showed that EV-induced iCAFs express IL-6 and activate the STAT3 signalling pathway that leads to EMT in bladder cancer." (PMID 36424598, 2022). "The biologicalactivity studies included the cytotoxicity, proapoptotic activity,and interleukin-6 release assays that were performed on primary andmetastatic cancer cell lines, as well as nontumor cells." (PMID 35071884, 2022). "Other immunoproteome biomarkers (IL-6, IL-10, MIP-1α) identified to be associated with genital inflammatory scores likely relate to cancer-induced inflammation rather than a host defense response to dysbiotic vaginal microbiota." (PMID 35196323, 2022). "By secreting IL-6, mutant KRAS cancer cells can activate Janus activated kinase 1 (JAK1) to induce the phosphorylation of the transcription factor signal transducer and activator of transcription 3 (STAT3) which is found in immune components such as macrophages of the TME." (PMID 36074553, 2022). "Evidence indicates that serum levels of IL-6 and TNF-α may be elevated in several cancers, and both proinflammatory cytokines present dichotomous since they have function that maintains the body's homeostasis." (PMID 35646122, 2022). "Particularly, CD163+ TAMs have been observed to secrete IL-6, which, upon binding of IL-6 receptor (IL6R) on the cancer cell surface, phosphorylate STAT3 (pSTAT3) that translocated to the nucleus and regulates the expression of varying microRNAs, including miR-506-3p, which promotes EMT." (PMID 36555840, 2022). "In addition, cytokines such as IL6 or IL23 and other molecules secreted by cancer cells or the TME also activate JAK/STAT." (PMID 35159370, 2022). "In conclusion, the network pharmacology of this study was used to screen out the active compounds of SBG (baicalein and wogonin), 41 intersection targets (VEGFA, IL6, MAPK3, JUN, TNF, and other targets), and 20 main pathways (Pathways in cancer, IL-17, TNF signaling pathway and others)." (PMID 36415861, 2022). "If systemic levels of protumor cytokines, such as IL6, are shown to be chronically elevated in those exposed to WTC dust, more frequent monitoring for cancer biomarkers such as PSA may be advisable to facilitate early detection of disease." (PMID 35911788, 2022). "Both in vitro and in vivo studies have been conducted, showing that, among others, Interleukin 6 (IL-6) released by the breast and prostate CSCs are responsible for maintaining a dynamic equilibrium between the cells with non-cancer stem cells (non-CSCs)." (PMID 35205721, 2022). "Macrophages that infiltrate the TME secrete cytokines, such as IL-6, IL-10, TNF-α, and TGF-β, which may enhance cancer cell stemness and EMT." (PMID 35565306, 2022). "Therefore, its potential as a therapeutic target for cancer has been indicated; furthermore, the antitumor effect of inhibiting the JAK/STAT3 pathway, which is the main signaling pathway of IL-6, has been reported." (PMID 35089951, 2022). "Our hypothesis was that concentrations of IL‐6 and TPO would be significantly higher in dogs with carcinoma when compared to healthy dogs." (PMID 34881459, 2022). "Further investigation into the synergistic relationship between IFN-γ and IL-6 may provide insight into how these ITGB4-targeted immunotherapies function in vivo, and potentially provide additional effort to improve cancer therapeutic efficacy." (PMID 34504657, 2021).
cancer (continued). "The results revealed that angiogenesis, glycolysis, and EMT were the biological process most correlated with CD44 expression, while the TNFα signaling via NFκB, angiogenesis, IL6_JAK_STAT3 pathway, and EMT were correlated with TNFRSF12A in cancer cells across CRC, LC, and SCC." (PMID 34676217, 2021). "Indeed, MDSCs secretes IL-6, which induces STAT3 phosphorylation, and activates Notch signaling, which enforces IL-6/STAT3 activation, thereby affecting cancer stemness." (PMID 35582386, 2021). "To expand upon the concept of using RPPA as a sensitive biomarker discovery platform for low-abundance antigens or proteins expressed by low-frequency cancer sub-clones, we studied the expression of two markers, IL-6 and TGF-β, reportedly shuttled in EVs and over-expressed in advanced cancers." (PMID 34155195, 2021). "In addition to IL-6, previous results reported the involvement of Interferon-γ (IFN-γ) in cancer cachexia." (PMID 34203023, 2021). "Furthermore, the M2 phenotype stimulates cancer stem cell self-renewal and growth via various signaling pathways e.g., EGF, TGF-β, IL-6 and IL-10, that lead to STAT3 activation." (PMID 33920983, 2021). "Several proinflammatory cytokines, including IL-1, IL-6, and TNF-α, may have important roles in the pathological mechanisms of cancer cachexia." (PMID 34502316, 2021). "This study reported for the first time that CK2 down-regulation in human cancer cells enhances the expression of SASP factors (IL-1β, IL-6, and MMP3) by NF-κB activation through two pathways: an SIRT1-dependent/AKT-independent pathway and an SIRT1/AKT-dependent pathway." (PMID 33401686, 2021). "It has been shown that IL-6 alone is sufficient to convert non-stem cancer cells to cancer stem cells and thus expand the cancer stem cell population in breast and prostate cancerss via an IL-6 feedback loop." (PMID 34588424, 2021). "The top amplified cancer genes were KRAS, CDK4, BRAF, IL6, TLK2 and MITF." (PMID 34313788, 2021). "The present prospective study of 232 patients with MBD in the extremities from various primary cancer types showed that elevated plasma IL-6, but not CRP and YKL-40, was an independent prognostic parameter for short OS." (PMID 34200156, 2021). "In addition to TGFB1 and IL10, gene expression of IFNG, IL6, and CXCL8 were all significantly increased (p < 0.05) in mesenchymal samples for more than half of the cancer types." (PMID 35096592, 2021). "With the same experimental design but in wild type mice, lycopene significantly exhibited anti-cancer property, mainly by inhibition of proinflammatory signaling as seen in a significant reduction in phosphorylation of NF-κB p65, STAT3, IL-6 and suppressed inflammatory foci." (PMID 34202203, 2021). "However, at a late stage when CCA is dominated by highly fibrotic areas, enriched in IL-6 producing CAFs, the expression of LC3 decreases while that of p62 increases, indicating an impairment of the autophagy process in cancer cells." (PMID 33925189, 2021). "We speculate that UPAL gel affects some cytokines, such as the suppression of IL-6 secretion in the TME, which inhibits the growth of cancer cells, while increasing the engraftment rate of implanted cells." (PMID 34439154, 2021). "The secretion of pro-stemness paracrine factors such as insulin-like growth factors, inflammatory cytokines (IL-6 and IL-8), and chemokines (CCL2 and CCL5) promotes the conversion of cancer cells into cancer stem cells and reinforce the stemness of existing cancer stem cells." (PMID 34094963, 2021). "With the same experimental design but in wild type mice, lycopene significantly exhibited anti-cancer property, mainly by inhibition of proinflammatory signaling as seen in significant reduction in phosphorylation of NF-κB p65, STAT3, IL-6 and suppressed inflammatory foci." (PMID 34202203, 2021).
cancer (continued). "In the current study, CN extracts were not affecting the proliferation and migration of cancer cells but suppressed the pro-inflammatory cytokines such as IL-6, IL-1β, and TNF-α." (PMID 34379689, 2021). "This transformation is caused by paracrine signalling from the TME, and it has been demonstrated that CAF-induced EMT was in fact dependent on TG2 expression mediated by IL-6 in hepatocellular carcinoma, positioning TG2 as critical for the cancer/CAF cross-talk within the TME." (PMID 34205140, 2021). "Moreover, through the secretion of IL-6, TGF-β cancer cells promote the accumulation of MDSCs, that, in turn, promote the expansion of Tregs." (PMID 34571894, 2021). "Psychosocial stressors in cancer promote inflammation and oxidative/nitrosative stress, with alterations in cytokine secretion and regulation (TNF-a or Il-6); decreased immunosurveillance; dysfunctional activation of the autonomic nervous system and hypothalamic–pituitary–adrenal axis." (PMID 35008225, 2021). "While preferentially dependent on canonical STING, we demonstrate that genotoxic DNA damage induced by camptothecin (CPT) also drove IL-6 production through non-canonical STING signaling in selected cancer cells." (PMID 35087822, 2021). "In conditions in which AR expression decreases, IL-6 expression may increase, thus leading to increased phosphorylation of STAT-3 and appearance of cancer stem cells." (PMID 34204596, 2021). "In addition, MSCs enhance cancer metastasis through releasing soluble factors such as chemokine SDF-1, IL-6 and CCL5." (PMID 33838662, 2021). "The IL-6/JAK2/STAT3 pathway plays a crucial role in the growth and development of many cancers." (PMID 34277446, 2021). "The significant decrease of IL-6 secretion was observed for both studied cancer cell lines in the presence of ART-LA (20 and 40 μM) without TRFi as compared to control (LA 20 μM) (p < 0.05, p < 0.01)." (PMID 34681200, 2021). "Our results suggest that 13R,20-diHDHA deregulates the dynamic equilibrium from non-stem cancer cells to CSCs by dephosphorylating Stat3 and decreasing IL-6 secretion, thereby inhibiting CSC formation." (PMID 33804152, 2021). "Unfortunately, long term administration of TZB can increase IL-6 levels through onset of CSCs, inducing a serious side effect, CRCC, and decrease anti-cancer efficacy by activating the NF-κB signaling and downstream apoptotic pathways in cancer patients." (PMID 34669701, 2021). "IL-6 induces the synthesis of CRP, a sensitive marker of cancer cachexia as well as inflammation." (PMID 33801569, 2021). "IL-6 also plays a role in cancer by stimulating the conversion of non-stem cell into stem-like cells." (PMID 33613850, 2021). "In GBM cell lines U-251 and U-87, the interaction of Ras (an oncogene) with TNFα/IL-1β was found to increase hypersecretion of IL-6/IL-8 cytokines and activation of the p38 MAPK signaling pathway, leading to the creation of an inflammatory microenvironment conducive for cancer progression." (PMID 34439380, 2021). "We demonstrate here that half of the STING-expressing cancer cells from the NCI60 panel rapidly increased expression of pro-tumorigenic IL-6 upon genotoxic DNA damage, often independent of type-I IFN responses." (PMID 35087822, 2021). "EC cells treated with cisplatin exhibit higher expression of IL-6, which promotes phosphorylation of STAT3 and thereby confers cancer hallmarks, including evasion of apoptosis and chemoresistance, on themselves or surrounding EC cells in autocrine or paracrine manners." (PMID 33816512, 2021). "For example, development of chronic inflammation via signalling molecules such as IL‐1A, IL‐6, IL‐8, CCL2 and CXCL is common in cancer patients, and consequences of systemic chemotherapy delivery are similar to those seen in ageing populations, such as frailty and insulin resistance." (PMID 34137158, 2021).